MST1 (macrophage stimulating 1)
Diseases named in the same sentence as MST1 in open-access papers (continued):
Sharing a sentence is not in itself a finding about the gene and the disease.
tumor (continued). "While the core module members MST1/2, Salvador, LATS1/2 and MOB1 have been attributed tumour suppressive functions, YAP/TAZ have been mainly described to have oncogenic roles, although some reports provided evidence supporting growth suppressive roles of YAP/TAZ in certain cancer settings." (PMID 25097725, 2014). "Changes to kinetochore–microtubule attachment stability and mitosis length are also reported in cells lacking proteins of the hippo tumor suppressor pathway: MST1, MST2, NDR1 and RASSF1A." (PMID 24898139, 2014). "Mst1 or Mst2 single knockout mice are viable and do not exhibit obvious organ overgrowth or tumor development, whereas Mst1 and Mst2 double-knockout (DKO) mice exhibit early embryonic lethality." (PMID 23985272, 2013). "Mst1 and Mst2 single knockout mice are viable and do not exhibit organ overgrowth or tumour development." (PMID 21102585, 2011). "This indicates that NaB may specifically affect certain components of the Hippo pathway, particularly those involved in tumor suppression, without altering MST-1 levels." (PMID 40872562, 2025). "Upon phosphorylation by Mst1/2 and Lats1/2, YAP/TAZ dephosphorylates and dissociates from cytoplasmic 14-3-3 kinase to enter the nucleus where it interacts with TEAD and other factors to initiate transcriptional expression of downstream target genes and promote stemness maintenance in tumor CSLCs." (PMID 38634107, 2024). "Overall, these studies highlight the importance of the MST1/2-Last1/2-YAP pathway in mediating the crosstalk between tumor cells and TAMs, ultimately influencing the polarization of TAMs towards either the M1 or M2 phenotype, which can have significant implications for tumor progression." (PMID 38090595, 2023). "Merlin, also known as the protein neurofibromin 2 (NF2), is a widely studied tumor suppressor that activates the Hippo pathway to inhibit YAP/TAZ activity via the mechanism of targeting LATS1/2 and improving the phosphorylation and activation of YAP/TAZ by MST1/2." (PMID 37243813, 2023). "Moreover, treatment with SHAP, a peptide-enhancing MST1/2 activity inhibited the tumor-killing ability of neutrophils (data not shown)." (PMID 36921037, 2023). "Several Hippo pathway tumor suppressors, including Lats2, Mst1, and Mst2, were also slightly increased in Vgll4 mutant livers, consistent with the well-established negative feedback whereby activation of the nuclear effector YAP leads to up-regulation of upstream tumor suppressors." (PMID 36522128, 2022). "Moreover, MST1-WT but not MST1-K59R blocked in vivo growth of tumor xenografts from WBP2-overexpressing MDA-MB-436 and HeLa cells." (PMID 32820148, 2020). "Therefore, we examined the levels MST1/2 and LATS1 kinases in ±DDR tumours +COL1." (PMID 32047176, 2020). "Second, SAV1 induces the protein kinase-phosphorylation cascade (MST1/2-LAST1/2-YAP/TAZ) in the Hippo pathway and simultaneously inhibits several other tumorigenic signal pathways, such as the AKT and NF-κB signal pathways in cancer cells, therefore amplifying SAV1-mediated tumor suppression." (PMID 32439835, 2020). "The localization of the MST1/2 and LATS1/2, whether it is cytoplasmic or nuclear, may impact the efficacy of the neoadjuvant therapy in breast cancer; being protective when expressed in the cytoplasm of tumor cells and in tumor-infiltrating lymphocytes." (PMID 29932172, 2018). "Targeting the core kinases of the Hippo signaling pathway, MST1/2 and LATS1/2, to activate YAP and TAZ activity could be desirable in regenerative medicine and in certain hematologic malignancies where YAP functions as a tumor suppressor." (PMID 27589805, 2016).
tumor (continued). "RASSF2 is another tumour suppressor silenced in renal cell carcinoma that was shown to bind and regulate the activation of MST1/2 and initiation of apoptosis, although it is not known whether this apoptosis is mediated by the MST/Hippo pathway." (PMID 27322327, 2016). "Acute Mst1/Mst2 deletion in the adult liver, achieved either by intravenous injection of adenovirus expressing Cre recombinase, or by tamoxifen induction of MMTV–CreERT or CAAGS–CreERT produced an intermediate tumour phenotype consisting of both HCC and mixed HCC/CC histology." (PMID 21102585, 2011). "Therefore, MST1 inhibition in the absence of YAP expression would not lead to tumor development." (PMID 31676778, 2019). "In this review, we first summarise the functions of the mammalian Hippo pathway in tumour formation, and then discuss non-cancer diseases involving Hippo signalling core components with a specific focus on our current understanding of the non-cancer roles of MST1/2 and YAP/TAZ." (PMID 25097725, 2014). "As a tumor suppressor within the non-classical Hippo pathway, RASSF1A maintains MST1/2 kinase activity through interaction via its SARAH domain." (PMID 40486910, 2025). "Immunoblot analyses of the ±DDR/−COL1 tumours revealed that neither DDR1b nor DDR2 expression altered the levels of either YAP1 and its phosphorylated forms, MST1 and MST2, LATS1 or KIBRA, when compared to tumours with repressed DDRs (+DOX)." (PMID 32047176, 2020). "Furthermore, through its conserved SARAH domain, RASSF family members form heterodimers with MST1/2 to modulate other non-classical apoptotic signaling pathways, such as the JNK/SAPK pathway, which further suppresses tumor cell proliferation." (PMID 40486910, 2025). "Importantly, these activities controlled by MST1 and MST2 in macrophages are independent of the canonical Hippo cascade that is known to limit tissue growth and tumor formation." (PMID 38624208, 2024). "Intriguingly, the treatment of Hippo pathway inhibitor, XMU-MP-1 (inhibiting MST1/2), could not recover the effect of PTTG3P on proliferation, apoptosis, and tumor growth." (PMID 34132347, 2021). "We found that S100A16 did not affect MST1/2 expression, but decreased LATS1 protein and MOB phosphorylation, which allowed YAP to enter the nucleus triggering the downstream targets CYR61 and CTGF, which are known to stimulate the angiogenesis and tumor growth 29,30." (PMID 37151881, 2023).
cancer (120 papers, 2008 to 2026). A tumor composed of atypical neoplastic, often pleomorphic cells that invade other tissues. "In cancers, however, dysregulation of Hippo signaling, often through the loss of kinases MST1/2 and LATS1/2, activates YAP/TAZ coactivators." (PMID 41155227, 2025). "In fact, whole‐genome sequencing of young patients with non‐small‐cell lung cancer detects mutations of HOXA4 as well as those of MST1, the upstream kinase of the Hippo signaling pathway, as cancer‐associated gene mutations." (PMID 32147946, 2020). "Hippo/YAP signaling pathway has been recognized as a linchpin in cancer therapy; dysregulation of core components (MST1/2, LATS1/2, YAP, etc.)associates with initiation, migration, invasion as well as therapeutic resistance of various types of cancer." (PMID 33292299, 2020). "Moreover, we further revealed that STRIPAK-mediated loss of MST1/2 activity can promote the DNA repair capacity of cancer cells to induce resistance towards radiotherapy and chemotherapy." (PMID 38657866, 2024). "Considering the hyperactive DNA repair capacity in MST1/2-deficient cells, we speculated that loss of the Hippo signal, which has been frequently observed in cancers, may endow cancer cells with resistance to radio- and chemotherapy." (PMID 35290241, 2022). "Furthermore, the upstream regulator of the Hippo pathway, ras association domain family (RASSF), suppresses cancer tumorigenesis by regulating MST1/2 activity." (PMID 33489905, 2020). "The deficiency of SAV1 in cancer cells causes the MST1/2 proteins to be inactive." (PMID 32439835, 2020). "However, total genetic ablation of Mst1 and Mst2 is also associated with the development of cancer in the liver and intestines." (PMID 31328787, 2019). "Although overexpression results have shown that nuclear MST1/2 can promote apoptosis, and reduced MST1/2 activity associates with poor cancer prognosis, the functional contributions of endogenous MST1/2 in physiological or pathological apoptosis remain elusive." (PMID 30903103, 2019). "Heterozygous and homozygous deletion of YAP dramatically suppresses tumorigenesis in LKB1-, Mob1-, and NF2-deficient liver, Mst1/2-deficient phenotypes in the small intestine and colon, and the early progression to pancreatic ductal adenocarcinoma in a Kras (G12D) cancer model." (PMID 28035075, 2017). "Chemical inhibitors of the STRIPAK complex are expected to activate MST1/2 and downstream signaling, and may have therapeutic potential in treating human cancers driven by NF2 mutations or elevated expression of YAP/TAZ." (PMID 29063833, 2017). "Macrophage-stimulated 1 (Mst1) has been identified as a novel upstream regulator of mitochondrial autophagy, which holds considerable importance in modulating apoptosis in cancer cells through the inhibition of mitochondrial autophagy." (PMID 40362504, 2025). "Members of the MARK subfamily, including MARK2, 3 and 4, regulate the Hippo kinase cassette in diverse models including Drosophila, mice and human cancer cell lines by phosphorylating MST1/2, SAV and, as found in a recent study, NF2 and YAP/TAZ." (PMID 40869130, 2025). "Glycogen LLPS can trigger the assembly of Laforin-Mst1/2 complex in glycogen droplets and inactivate Mst1/2, thereby activating Yap to promote the survival and growth of cancer cells." (PMID 40231263, 2025). "The pro-apoptotic activity of MST1/2 has been characterized in cancer cell lines or fibroblasts by overproducing the kinases or gene knockdown methods (12, –, 16)." (PMID 38624208, 2024).
cancer (continued). "Ectopic overproduction of MST1 or MST2 in cell lines promotes apoptosis (12, –, 16), and elevated YAP1 protein levels are associated with human cancers, suggesting that MST1/2 possess pro-apoptotic activities to limit cell proliferation and tumors." (PMID 38624208, 2024). "The up-regulation of Ras-association domain family (RASSF) 4, a member of RASSF, by PAX3-FOXO1, inhibited MST1 activity, which induced senescence avoidance and promoted cancer through cell cycle progression." (PMID 39791714, 2024). "Hippo-YAP pathway was targeted in both models by using siRNA-induced Mst1-knockdown in cancer cells, Mst1 kinase-dead (dnMst1-TG) mouse model 25, and verteporfin as a specific inhibitor for YAP-TEAD transcriptional activity." (PMID 36632235, 2023). "A prominent example is the isoform switch in the STK4 gene (frequently called MST1) found in three cancer types: thyroid, kidney and colorectal." (PMID 37745975, 2023). "DOX (1 μM) stimulation significantly activated Hippo pathway in cancer cells manifested as increased levels of Mst1 protein and Ser127-pYAP while total YAP expression decreased." (PMID 36632235, 2023). "Thus, selective upregulation of NUMB3/4 expression along with a reduction of p-SPTAN1 might be an important mechanism of suppression of MST1/2 activity, leading to loss of cell-cell contact inhibition of cell growth during the initiation and progression of cancer." (PMID 37843276, 2023). "MST1/2 were reported to be activated in immortalized or cancer cell lines including HEK293 and MCF10A under confluent conditions compared with cells under sparse conditions." (PMID 37843276, 2023). "Precipitation of cancer cell lysates with an antibody against PP2A also enriched for precipitated MST1 and SIRPγ." (PMID 35229723, 2022). "As such, we found that STRIPAK-mediated MST1/2 inactivation increased the DSB repair capacity of cancer cells and endowed these cells with resistance to radio- and chemotherapy and poly(ADP-ribose)polymerase (PARP) inhibition." (PMID 35290241, 2022). "Mammalian STE20-like kinase 1 (MST1), a core component of the Hippo signaling pathway, was originally considered a proapoptotic kinase that plays a crucial role in modulating cancer cell growth and proliferation." (PMID 34522213, 2021). "As a core kinase of the Hippo signaling pathway in cancers, MST1/2 participates in the development and function of Treg and Th17 cells." (PMID 34267752, 2021). "The mutation and expression changes of its core components (MST1/2, LATS1/2, YAP, and TAZ) can promote the migration, invasion, and malignant progression of cancer cells." (PMID 34447747, 2021). "But in cancer cells, they override the negative regulation of MST1/2, LATS1/2, MOB1 and SAV1, and result in inactivation of Hippo kinase cascade which leads to nuclear translocation of YAP and TAZ and the expression of downstream targets." (PMID 31941533, 2020). "It should be noted that cytoplasmic expression of MST1 in cancer cells has been related with its function as a protective molecule acting in the canonical Hippo signaling pathway, through the inhibition of oncogenic YAP/TAZ." (PMID 32218280, 2020). "Pathway analysis also revealed that the hypomethylated, upregulated genes were enriched in MST1 signaling, which has demonstrated significant effects in multiple types of human cancer." (PMID 31889904, 2019). "Mutations and altered expression of its core components (MST1/2, LATS1/2, YAP and TAZ) promote the migration, invasion, malignancy of cancer cells." (PMID 30961610, 2019). "Studies have consistently shown that inactivation of Hippo signaling by downregulation of the Hippo pathway components mammalian MST1/2 andLATS1/2 contributed to resistance of cancer cells to chemotherapeutic drugs." (PMID 29439714, 2018). "The group of cancer death within 5 years showed significantly lower MST1 expression than the group lived over five years after diagnosis (p = 0.0027)." (PMID 29079854, 2017).
cancer (continued). "Dysregulation of MST1/STK4, a key kinase component of the Hippo-YAP pathway, is linked to the etiology of many cancers with poor prognosis." (PMID 28880957, 2017). "Thus, targeting MST1/2 holds significant research and clinical value, potentially bridging basic and clinical medicine to offer new cancer treatment strategies." (PMID 41144784, 2026). "Similarly, its cytoskeletal role via MST1/DOCK8/WASP expands upon HMGB1’s known capacity to modulate cell migration in cancer and endothelial cells." (PMID 40985892, 2025). "It has been shown that Mst1 directly inhibits Akt in cancer cells." (PMID 39060225, 2024). "On the other hand, Mst1 activation inhibits NF-κB activation in fibroblasts and cancer cells." (PMID 39253972, 2024). "Deregulation of the Hippo pathway is one event contributing to cancer development and leading to a kinase cascade in which macrophage stimulating 1/2 kinases (MST1/2) phosphorylate large tumor suppressor kinase 1/2 (LATS1/2) and Salvador family WW domain containing protein 1 (SAV1)." (PMID 38388496, 2024). "Importantly, NUMB3/4 isoforms that fail to interact with SPTAN1 and activate MST1/2 are predominately upregulated in cancer cells." (PMID 37843276, 2023). "NUMB3/4 isoforms that fail to activate MST1/2 are dominantly expressed in cancer cells." (PMID 37843276, 2023). "More remarkably, our results in human heart samples suggest that new therapies targeting MST1 may be potentially helpful for improving the cardiac prognosis of cancer patients treated with DOX." (PMID 37566283, 2023). "Given this association and the increased expression in cancer, we posited that MST1R and MST1 genes may be co-regulated and that certain genomic alterations may dually affect expression." (PMID 35626096, 2022). "Furthermore, SIRPγhi cancer cells displayed decreased p-MST1, p-LATS1, and p-YAP, and enhanced SOX2 expression compared with SIRPγlo/– cells." (PMID 35229723, 2022). "Increases in YAP-1 activity are associated with cell proliferation and cancers, whereas phosphorylation of YAP-1 via MST1/2-LATS1/2 results in its cytoplasmic retention, and subsequent degradation, leading to loss of transcriptional activity and induction of apoptosis." (PMID 35846360, 2022). "Recent studies have shown that MST1 not only has a major regulatory capacity for embryonic development and tissue remodeling, but also plays a significant role in cancer and benign diseases with cancer biological behavior." (PMID 36263059, 2022). "Studies herein are the first to report correlated co-expression of MST1R and MST1 across nearly all cancer types and are consistent with a previous study that reported a lack of alterations using polymerase chain reaction-single strand conformational polymorphism (PCR-SSCP) analysis." (PMID 35626096, 2022). "Overexpressed MST1 reportedly suppresses cancer cell proliferation, migration, and invasion." (PMID 34522213, 2021). "Additionally, the loss of RASSF1A pro-apoptotic signalling can occur by the loss of expression of MST1/2 and LATS1/2 in some cancer types." (PMID 31963420, 2020). "Therefore, upregulation of SAV1 expression and subsequent activation of the MST1/2-LAST1/2 complex in cancer cells are important treatment strategies to be explored." (PMID 32439835, 2020). "Recent studies have reported that mutations in the Hippo signaling components SAV1, MST1/2 and Lats1/2 are not evident in human cancer." (PMID 30961610, 2019). "As MDA-MB-453 and ZR-75.1 both contain the cancer-associated FGFR4-R388 (MDA-MB-453, homozygous; ZR-75.1, heterozygous), we further silenced FGFR4 in BT474 homozygous for FGFR4 G388, which increased MST1/N as well as full-length MST1/2, indicating that both FGFR4 variants can suppress MST1." (PMID 30903103, 2019). "However, in the mouse models, it requires both Mst1 and Mst2 to be completely ablated during embryonic development to produce cancer in the adult." (PMID 31328787, 2019).